IL1B (interleukin 1 beta)
Diseases named in the same sentence as IL1B in open-access papers (continued):
Sharing a sentence is not in itself a finding about the gene and the disease.
peritonitis (continued). "Silva and coworkers (2014) reported that pretreatment with myrtenol reduced IL-1β levels in peritoneal lavage of mice submitted to carrageenan-induced peritonitis." (PMID 35712716, 2022). "We conclude that neutrophils orchestrate acute thioglycollate-induced peritonitis by producing IL-1β in an NLRP3-dependent manner." (PMID 36494392, 2022). "The injection of MSU or CPP crystals caused a leucocyte infiltration and an increase in IL-1β, CXCL1, IL-6, TNF-α, and VEGF in lavage fluids from mice with peritonitis, which diminished in the presence of BPI." (PMID 36361854, 2022). "To assess the direct contribution of neutrophils to the production of IL-1β, we induced thioglycollate-induced peritonitis in neutrophil-depleted mice using anti-Ly6G antibody." (PMID 36494392, 2022). "MSU crystal-induced peritonitis is another well-established NLRP3-dependent acute inflammatory model characterized by IL-1β secretion and massive neutrophil infiltration in peritoneal cavity." (PMID 35250572, 2022). "We evaluated eryptosis percentage, CRP, IL-6, and IL-1β levels in the PD controls and in the PD patients with peritonitis on the first day of peritonitis." (PMID 36498493, 2022). "We focused mainly on the process of early neutrophil recruitment and the role of neutrophils in IL-1β generation by using a mouse thioglycollate-induced peritonitis model in the first 4 h." (PMID 36494392, 2022). "In the present study, using a murine model of LPS-induced acute peritonitis, we demonstrated administration of IL-10 inhibits inflammatory response via reduction of proinflammatory cytokines, including IL-1β, IL-18, and TNF-α in PLF and serum." (PMID 33414479, 2021). "The production of IL-1β in peritonitis and septic shock induced by i.p. injection of LPS is associated with NLRP3 inflammasome activation." (PMID 33414479, 2021). "Injecting LPS into the abdominal cavity of mice can cause peritonitis and a significant increase in cytokines in mice, including IL-6, IFN-γ, IL-1β, nitric oxide (NO), and TNF-α." (PMID 34884814, 2021). "In another MSU-induced peritonitis model, PL exhibited similar effects by suppressing IL-1β production and neutrophil infiltration, both of which were dependent on NLRP3 inflammasome." (PMID 35095532, 2021). "To understand the transcriptional correlates of recruitment to inflamed tissues, we characterized neutrophils from IL-1β peritonitis, IL-1β pneumonitis, and immune-complex arthritis." (PMID 34001893, 2021). "Chimeric Atg5ΔEC mice exhibited enhanced neutrophil infiltration in an LPS-driven peritonitis model and in cutaneous models of inflammation as induced by locally injected LPS and interleukin-1β (IL-1β)." (PMID 34363750, 2021). "In the absence of the Trx1 system, we observed drastically impaired IL-1β production in response to classical NLRP3 stimuli in vitro and during MSU-induced peritonitis in vivo, while pro-Il1b transcription was unaltered." (PMID 32096759, 2020). "A mouse model of MSU-induced peritonitis characterized by massive neutrophil influx and IL-1β production was established to define the suppressive effects of KM on the NLRP3 inflammasome in vivo." (PMID 33542692, 2020). "Further study found that KM also robustly inhibited neutrophil infiltration and IL-1β production in an MSU-induced peritonitis model." (PMID 33542692, 2020). "T-bet deficiency also dramatically relieved MSU-induced inflammatory cell infiltration in peritonitis and air pouch models in vivo, and as well as the IL-1β levels of air pouch lavage fluid (APLF)." (PMID 31231373, 2019). "In peritonitis, treatment with the extract at a dose of 500 mg/kg resulted in a lower total leukocyte count in the peritoneal fluid and blood and lower levels of IL-1β, IL-6, TNF-α and PGE-2 than the control group." (PMID 31830043, 2019).
peritonitis (continued). "Early production of CCL3, as well as CCL2 and cytokines such as IL-1β, IL-6, IL-12, and IL-1Ra, was observed in an acute antigen-induced peritonitis model, showing that peritoneal-resident cells are an important source of these mediators." (PMID 30937315, 2019). "We then investigated the activity of APO on IL-1β release in vivo in the MSU-induced peritonitis mouse model." (PMID 29686531, 2018). "Dopamine-mediated DRD1 signaling also prevents both LPS-induced systemic inflammation and MSU-induced peritonitis through suppression of IL-1β production via inhibition of NLRP3 inflammasome activation, but not by suppression of TNF-α." (PMID 29868015, 2018). "Intraperitoneal injection of MSU elicited an NLRP3‐dependent peritonitis characterized by IL‐1β production and massive neutrophil influx." (PMID 29531021, 2018). "Collectively, these data indicated that BOT-4-one has a useful protective effect on MSU-induced peritonitis by inhibiting the NLRP3 inflammasome-mediated IL-1β production." (PMID 29118366, 2017). "Consistent with that, TRIM31 deficiency facilitated NLRP3 inflammasome activation, enhanced IL-1β secretion and thus aggravated alum-induced peritonitis in vivo." (PMID 27929086, 2016). "Using a GBS-induced peritonitis model in mice, we first found that a large proportion of exudate cells contain intracellular IL-1β by immunofluorescence." (PMID 27509078, 2016). "This agrees with our results showing that blockade of NLRP3 inflammasome with glybenclamide in the ITO-NP–mediated peritonitis mouse model principally reduced the influx of neutrophils and IL-1β production." (PMID 27194621, 2016). "The importance of PR3-mediated IL-1β processing has also been demonstrated in peritonitis induced by intraperitoneal challenge with monosodium urate crystals, a self-derived molecule relevant to gout." (PMID 26549942, 2015). "In vivo, we showed that genipin inhibited NLRP3-dependent IL-1β production and neutrophil flux in LPS- and alum-induced murine peritonitis." (PMID 26659006, 2015). "In vivo, elevated urate and XO activity levels were also correlated to IL1β in peritoneal washes taken from mice during OCP-induced peritonitis." (PMID 25800347, 2015). "To extend our studies we have also investigated the consequence of the loss of TG2 on MSU crystal-induced IL-1β and TGF-β1 formation in an in vivo mouse peritonitis model by using TG2-null animals." (PMID 25889736, 2015). "A dominant role of IL-1α compared to IL-1β has been demonstrated in nano-TiO2-induced peritonitis and lung neutrophilic inflammation by using IL-1R-, IL-1α- or inflammasome component-deficient mice." (PMID 25497724, 2014). "SOD3 expression significantly reduced the number of peritoneal infiltrating cells in proteose peptone and IL-1β induced peritonitis in wild type mice." (PMID 22529530, 2012). "Increased synthesis of hyaluronan in mesothelial cell during peritonitis is attributed to their induction by proinflammatory cytokines and growth factors, in particular, IL-1β IL-6, TNF-α, TGF-β1, and PDGF." (PMID 22577250, 2012). "Further studies are needed to reveal which molecular mechanisms account for the increased IL-1β processing and export in peritonitis pMφ." (PMID 22481867, 2012). "Of note, mice submitted to carrageenan-induced peritonitis exhibited increased IL-1β and TNF-α levels, in contrast to reduced IL-10 levels in peritoneal fluid." (PMID 21799673, 2011). "Similar findings have been reported in other chronic inflammatory models, where ANXA1-deficient animals exhibited exacerbated inflammatory responses in carrageenan-induced edema and zymosan-induced peritonitis models, with increased leukocyte migration and IL-1β production." (PMID 41200163, 2025). "Additionally, Zdhhc7 KO mice were more resistant to MSU-induced peritonitis, with lower neutrophil and macrophage infiltration in peritoneal lavage fluid and diminished IL-1β levels in the serum of Zdhhc7 KO mice." (PMID 38583156, 2024).
peritonitis (continued). "However, extravascular (i.p.)injection of RGD peptides rescued the defective neutrophil accumulation in Pecam1-/- mice upon IL-1β-induced peritonitis." (PMID 37549051, 2023). "Third, since IL-1β-positive MV-induced endothelial activation appeared partially IL-1-dependent in vitro, we showed for the first time that IL-1β-positive MVs exert an IL-1-mediated pro-inflammatory effect in vivo in a murine model of sterile peritonitis." (PMID 38077384, 2023). "TMs decreased the association of HuR with genes involved in chemotaxis and immune response, including Cxcl10, Il1b and Cd40, reducing their expression and protein secretion in primary murine bone marrow-derived macrophages and in an LPS-induced peritonitis model." (PMID 36912171, 2023). "It has long been known that the intraperitoneal administration of zymosan, a particulate compound extracted from the yeast cell wall and containing β-1,3/1,6 glucans, induces peritonitis and, consequently, the release of inflammatory cytokines, including IL-1β." (PMID 36605196, 2022). "ethanol extract could exhibit an anti-inflammatory effect by inhibiting the production of several proinflammatory mediators, including NO, TNF-α, IL-1β, and IL-6 in LPS-induced peritonitis in vivo and in vitro." (PMID 34931128, 2021). "Furthermore, KM treatment efficiently attenuated the infiltration of neutrophils and suppressed IL-1β production in mice with MSU-induced peritonitis." (PMID 33542692, 2020). "Furthermore, the anti-inflammatory properties of 4-HAB were confirmed in a mouse model of uric acid crystals-mediated peritonitis by the reduced levels of neutrophil influx, IL-1β, active caspase-1, IL-6 and MCP-1 in lavage fluids." (PMID 31979265, 2020). "Furthermore, adoptive transfer of IL-33-induced MDSCs (CD11b+Gr1intF4/80+) markedly inhibited IL-1β production in MSU-induced peritonitis." (PMID 30863362, 2019). "Interestingly, a large number of CD11b+Gr1intF4/80+ MDSCs was detected in the IL-33-treated mice, and adoptive transfer of IL-33-induced MDSCs markedly inhibited the IL-1β production in MSU-induced peritonitis." (PMID 30863362, 2019). "Attenuating the release of the inflammatory mediator, IL-1β in MSU-induced peritonitis mouse model could represent a potentially effective treatment by APO for gout-related disorders." (PMID 29686531, 2018). "To check the in vivo relevance of inhibitory action of ALE on IL-1β release, we examined whether ALE treatment could suppress the elevated plasma level of IL-1β in LPS-induced mouse peritonitis model." (PMID 29576797, 2018). "In addition, ALE significantly reduced the LPS-induced increase of plasma IL-1β in mouse peritonitis model." (PMID 29576797, 2018). "Moreover, the IL-1β levels of lavage fluids in the air pouch and peritonitis models from miR-155 KO mice were almost the same as those from WT mice." (PMID 29996893, 2018). "The in vivo model of MSU-induced peritonitis allowed to evidence that both IL-1α and IL-1β production was reduced at an early phase in CalpTG mice, suggesting that calpains actually promote IL-1α and IL-1β synthesis in response to cellular stress in vivo." (PMID 28808241, 2017). "In addition, we assessed IL-α and IL-1β synthesis at an early phase in a monosodium urate (MSU) peritonitis model." (PMID 28808241, 2017). "Furthermore, STIM2-deficient animals showed decreased macrophage recruitment in the model of Thg-induced peritonitis and reduced TNFα, IL-6, and IL-1β serum levels in LPS-induced inflammation." (PMID 26417434, 2015). "We have shown that an Sph analogue, FTY720, induced IL-1β secretion from LPS-primed peritoneal macrophages in vitro, and also that it induced IL-1β release and neutrophil influx in an in vivo model of peritonitis, hallmarks of DAMPs such as MSU and DAMPs released from dead cells." (PMID 22105559, 2012). "Similarly, in a ZYM-induced peritonitis model, ouabain could reduce IL-1β by inhibiting NF-κB activation." (PMID 39329752, 2024).
peritonitis (continued). "The thioglycollate-induced peritonitis model (at 4 h) has been characterized as neutrophil-dominant inflammation, and it is reasonable to speculate that the high number of neutrophils in the peritoneal cavity are the sources of the IL-1β." (PMID 36494392, 2022). "Besides that, a large number of anti-inflammatory MDSCs with CD11b+Gr1intF4/80+ phenotype was observed in the IL-33-treated mice, and adoptive transfer of IL-33-induced MDSCs (CD11b+Gr1intF4/80+) markedly inhibited the IL-1β production in MSU-induced peritonitis." (PMID 30863362, 2019). "It reduces IL‐1β and IL‐18 production in human monocytes and attenuates caspase‐1 activation and IL‐1β secretion in mouse models of NLRP3‐associated diseases, such as Muckle–Wells syndrome, familial cold autoinflammatory syndrome, and urate crystal‐induced peritonitis." (PMID 30224384, 2018). "In turn, in the mice peritonitis models, RvD2 (1 μg/mouse) decreased the level of IL-1β, IL-6 and TNF-α in LPS-treated mice but only affected IL-1β in mice injected with monosodium urate or alum." (PMID 38542895, 2024). "The oral treatment of acute peritonitis with HEVe reduced the total leukocytes, neutrophils, TNF-α, and IL-1β and elevated IL-10 levels." (PMID 39452085, 2024). "The gene transcription of CAR, IL-1b, and TNF-a was significantly increased in the PMCs of peritonitis mice compared to wild-type mice." (PMID 36982385, 2023). "Flow cytometry analysis of peritoneal cells and measurement of IL-6, IL-1β, and TNF-α levels in the peritoneal lavages confirmed zymosan-induced peritonitis." (PMID 36769096, 2023). "Similar to the in vitro effects, Crocin attenuated the secretion of IL-1β and IL-18 and neutrophil recruitment in an MSU-induced mouse peritonitis model." (PMID 36975504, 2023). "The serum levels of TNF-α, IL-1β, IL-6, and IL-10 in rats with systemic inflammation, and the levels of TNF-α in a model of acute peritonitis in rats were also investigated." (PMID 37103384, 2023). "Dialysate levels of cytokines, such as IL-1β, IL-6, and transforming growth factor-β (TGF-β), increase markedly on the first day of peritonitis, and then their concentrations decrease gradually." (PMID 36498493, 2022). "A peritonitis model in C57BL/6 mice was used to assess the role of Mito-TEMPO or Mdivi-1 on inflammatory cell influx and IL-1β production." (PMID 36338340, 2022). "Our results showed that TAK 242 significantly inhibited the production of inflammatory cytokines in the peritoneal lavage fluid of mice with peritonitis, including IL-6, IFN-γ, IL-1β, NO, and TNF-α." (PMID 34884814, 2021). "In another MSU-induced peritonitis model, PL also exhibited inhibitory effects on NLRP3 inflammasome reflected by reduced IL-1β and recruitment of neutrophils in the lavage fluid." (PMID 35095532, 2021). "Using adoptive transfer of SOCS3-silenced macrophages in a mouse peritonitis model, the investigators demonstrated that SOCS3 drives the production of M1-induced cytokines (TNF-α, IL-1β), while reducing the expression of M2-induced IL-10." (PMID 34339354, 2021). "Based on the findings of a previous study showing that an MSU-induced model of peritonitis is dependent on NLRP3 inflammasome activation, the levels of inflammatory indicators of peritonitis: peritoneal neutrophils and IL-1β were analyzed." (PMID 34512673, 2021). "In this study, we further found that KM potently inhibited IL-1β production and neutrophil influx in MSU peritonitis." (PMID 33542692, 2020). "Another study showed that in a mouse peritonitis model, FICZ reduced inflammasome activation and reduced IL6, IL-1β and TNFα levels." (PMID 32439897, 2020). "Compared with those of the control mice, IL-1β levels and the numbers of PECs, neutrophils and macrophages were all decreased in acetate-treated mice during MSU- or alum-induced peritonitis." (PMID 31337751, 2019).
peritonitis (continued). "V. polysphaera extract substantially reduced the levels of proinflammatory mediators such as TNF-α, IL-1β, IL-6 and PGE-2 in λ-carrageenan-induced peritonitis when compared to the stimulated and untreated group." (PMID 31830043, 2019). "It has been well described that leukocyte recruitment and inflammation maintenance involve proinflammatory cytokines such as IL-1β, IL-6, and TNF-α in zymosan-induced peritonitis." (PMID 31236418, 2019). "In an MSU-induced peritonitis mouse model, SFN reduced the number of peritoneal exudate cells (PECs) and IL-1β secretion in the peritoneal fluid and serum." (PMID 30514828, 2018). "The peritonitis experimental model was induced by carrageenan following of Myeloperoxidase activity (MPO), Total glutathione and malondialdehyde (MDA), IL-1β and TNF-α levels by spectroscopic UV/VIS analysis." (PMID 29523111, 2018). "In vivo evaluation revealed that intraperitoneal administration of APO reduced IL-1β levels, significantly (p < 0.05) and dose dependently, in the MSU-induced peritonitis mouse model." (PMID 29686531, 2018). "Although the in vitro inhibitory activity of TR on MSU‐induced IL‐1β secretion was around 400 times less potent than MCC950, its in vivo activity on MSU‐induced peritonitis was only around 5–10 times less potent than MCC950." (PMID 29531021, 2018). "In a mouse model, we found that PF-562271 can inhibit NLRP3-mediated IL-1β secretion and reduce MSU-induced peritonitis." (PMID 27796369, 2016). "In the acute peritonitis mouse model, MCL reduced the secretion of IL-6, TNF-α, IL-1β, MCP-1, IFN-β and IL-10 in sera, and ameliorated lung and liver damage." (PMID 26984741, 2016). "Here, mice intraperitoneally inoculated with ITO-nanoparticles (ITO-NPs) resulted in peritonitis dependent in NLRP3 inflammasome, with neutrophils recruitment and interleukin-1β (IL-1β) production." (PMID 27194621, 2016). "Using the in vivo peritonitis model, we confirmed XOR inhibition by allopurinol in OCP-treated mice decreased IL1β and urate levels in the peritoneal lavage, while cellular recruitment remained unchanged." (PMID 25800347, 2015). "A study done in the rat CLP peritonitis model demostrated a decrease of TNF-α and IL-1β in lungs of animals receiving a prolonged three week pre-treatment with probiotics and overall reduction of acute lung injury was also observed." (PMID 24830455, 2014). "Consistent with our in vitro observations, cells isolated from mice with MSU crystal-induced peritonitis showed significantly increased mRNA levels of TNF-α and IL-1β." (PMID 24708712, 2014). "In an in vivo model of peritonitis, the water-soluble Sph analogue FTY720 induced IL-1β release and neutrophil influx into the peritoneal cavity." (PMID 22105559, 2012). "Apart from hyaluronan, mesothelial cells also synthesize and secrete TGF-β1, IL-1β, IL-6, and TNF-α and their levels are increased during peritonitis." (PMID 22577250, 2012). "In vivo (LPS-induced peritonitis), MCHLE reduced total leukocyte and neutrophil influx and lowered TNF-α and NO levels to values comparable to dexamethasone; in vitro (LPS-stimulated RAW 264.7), it produced dose-dependent inhibition of TNF-α, IL-1β, and NO." (PMID 41302395, 2025). "On the other hand, the oil reduced inflammation in two murine models of inflammation: carrageenan-induced peacock edema (the oil reduced peacock skin thickness and expression of IL-6 and IL-1β) and thioglycollate-induced peritonitis (TNF-α, IL-1β and IL-6 levels were reduced in peritoneal fluid)." (PMID 38473970, 2024). "In the peritonitis mouse model characterized by a macrophage phenotype, DW18134 effectively reduced the behavioral score of the peritonitis mice and the secretion of inflammatory factors TNF-α, IL-6, and IL-1β in the serum, with therapeutic efficacy comparable to PF-06650833." (PMID 38675622, 2024).